IRF3 (interferon regulatory factor 3)
Diseases named in the same sentence as IRF3 in open-access papers (continued):
Sharing a sentence is not in itself a finding about the gene and the disease.
viral infection (continued). "IRF-3 is indispensable for IFN-β production upon viral infection, further emphasizing the significant role of FHL2 in regulating IFN-β responses." (PMID 38203523, 2023). "A viral infection activates the transcription factors IRF3 and NF-κB, which synergistically induces type I interferons (IFNs)." (PMID 38003298, 2023). "Confocal microscopy showed that more IRF3 translocated to the nucleus with overexpressing OTUD6B upon viral infection as measured using mean fluorescence intensity (MFI), the MFI value changed from 8,965 to 11,260." (PMID 37650650, 2023). "SETX is indeed able to attenuate the transcription of IRF3-dependent antiviral genes during the early phase of viral infection." (PMID 37147318, 2023). "Upon viral infection, IRF3 is phosphorylated and forms dimers to enter the nucleus to activate IFN transcription." (PMID 37410776, 2023). "There were some reports that the inhibition of the interaction of HSP90A with TBK1, IRF3, and Cdc37 impairs the innate immune response to viral infection." (PMID 37442062, 2023). "Taken together, deficiency of Smyd2 promotes phosphorylation of IRF3 in macrophages in response to virus infection, which leads to increased translocation of dimerized IRF3 to the nucleus to promote IFN-I production." (PMID 37673879, 2023). "Recently, MEKK2 from tumor-derived exosomes has been shown to phosphorylate IRF3, which then promotes IRF3 polyubiquitylation and blocks its dimerization, nuclear translocation, and transcriptional activity following virus infection." (PMID 36498930, 2022). "The strong dependence of chromatin accessibility on MAVS and IRF3 supported that extranuclear signaling pathways conferred a requirement for remodeling of chromatin after viral infection." (PMID 35658050, 2022). "Viral infection can cause upregulation of OTUD1, and OTUD1 as a DUB can attenuate the K6-linked ubiquitination of IRF3 to affect the DNA-binding ability of IRF3, thereby antagonizing the IRF3-mediated innate immune pathway." (PMID 36505476, 2022). "As a result, the IRF3-dependent production of interferons and pro-inflammatory cytokines is attenuated, leading to increased viral infection sensitivity." (PMID 35136173, 2022). "Upon viral infection, phosphorylated IRF3 forms complex with co-activator CBP/p300, then the complex translocates to the nucleus and binds the regulatory domains of the IFN-β promoter to initiate transcription of IFN-β." (PMID 35248104, 2022). "In response to viral infection or nucleic acid exposure, IRF3 hyperphosphorylate, dimerize and translocate to the nucleus as an active transcription factor." (PMID 35632751, 2022). "In this study, we demonstrated that TOB1, which is induced during viral infection, inhibited IRF3-directed IFN responses and antiviral immunity." (PMID 36085336, 2022). "Following virus infection Irf3-/-xIrf7-/-DKO mice had similar levels of IFN mRNA induction compared to B6 mice with either JCV or INKV infection, while the Mavs-/-xUnc93b1.3D mice had little to no IFN mRNA upregulation in response to infection." (PMID 35245345, 2022). "Despite that IRF8 is found to be partially localized in cytoplasm, the nuclear-localized IRF8 works with IRF3 to enable rapid IFN gene transcription in human blood monocytes following viral infection." (PMID 35464458, 2022). "This serine/threonine protein kinase has a key role in innate immunity, in particular during viral infections, as it coordinates the activation state of IRF3 (Interferon Regulatory Factor 3) and NF-κB." (PMID 35203299, 2022). "Although these studies illustrate the critical role of IRF7 in human viral disease, compared to IRF3, especially in human, much less is known about how IRF7 is regulated." (PMID 35013241, 2022). "Degradation of WTAP induced by viral infection reduces the m6A levels of interferon-regulatory factor 3 (IRF3) and interferon α/β receptor subunit 1 (IFNAR1) mRNAs, resulting in the suppression of IRF3 translation and destabilization of IFNAR1 mRNA." (PMID 36582239, 2022).
viral infection (continued). "Yet, it is also conceivable that upon viral infection Cxcl9+ FRCs represent LNSCs that can acquire anti-viral properties, which was simulated by Irf3 and Irf1 overexpression in the MSC cell line." (PMID 36433946, 2022). "Together, these results reveal that the ASFV I226R protein impairs antiviral responses, likely through multiple mechanisms including the suppression of NF-κB and IRF3 activation, to counteract innate immune responses during the viral infection." (PMID 35336982, 2022). "IRF1 also plays a positive regulatory role in the innate immune response to viral infection by enhancing the phosphorylation of IRF3 and the production of types I and III IFN triggered by viral infection." (PMID 35379320, 2022). "As a key transcription factor of the innate immune response, interferon regulatory factor 3 (IRF3) plays an important role in the resistance and control of viral infections." (PMID 35037825, 2022). "Third, phosphorylation of IRF3Y107 by SRC was important for IRF3 association with TBK1 and its self-association, as well as induction of IFN-β upon viral infection." (PMID 35468896, 2022). "We found that viral infection-induced TOB1 interacted with IRF3 and bound to the promoter region of Ifnb1, leading to recruitment of HDAC8 and suppression of IFN-β production." (PMID 36085336, 2022). "A large percentage of immune genes in humans are also controlled by NF-kB transcription factors upon induction by bacterial infection, and by IRF3/7 upon viral infection, working together with NF-kB56–59." (PMID 35013162, 2022). "RIG-I can be activated by invading viral agents and then induce Interferon (IFN) production to resist the viral infection by facilitating phosphorylation of IRF3." (PMID 36232585, 2022). "Upon infection, inhibition of interferon regulatory factor 3 (IRF3) by viral infection is a critical link for the termination of the type I interferon pathway." (PMID 36531988, 2022). "The influence of EGb on inflammatory-associated genes expression that regulate innate immune response to viral infection and cytokine production, namely IRF-3, IRF-7, tetherin, SOCS1, SOCS3, NFKB1, p65, and MxA was also examined." (PMID 35631163, 2022). "It has been previously reported that HO-1 is required for the activation of IRF3 after viral infection." (PMID 35180274, 2022). "IRF3 is subjected to viral infection-induced K6-linked ubiquitylation which is recognized and cleaved by OTUD1 in a way that impairs the capacity of IRF3 to bind to the promoter region of its target genes.." (PMID 35136173, 2022). "In this process, IRF3 plays an important role in the production of type I IFNs induced by virus infection." (PMID 35573779, 2022). "STING was originally identified as a cytosolic nucleic-acid sensor, which triggering leads to the induction of a robust type I IFN response via IRF3 and NFkB, and a rapid antiviral state that enables the control of viral infections." (PMID 36278864, 2022). "In this regard, regulating IRF3 activation has become the target of therapeutic strategies for viral infections and autoimmune diseases." (PMID 35573779, 2022). "IRF3, in addition to virus infection, can also be activated by bacterial infections such as Listeria, Mycobacterium, or Neisseria to promote bacterial pathogenesis." (PMID 36507301, 2022). "p62 has been reported to control IFN antiviral responses by promoting autophagic degradation of several key factors in the IFN pathway, including RIG-I, cGAS, MAVS, and IRF3 during viral infection." (PMID 35865923, 2022). "During viral infection, K63-linked polyubiquitination of TRAF3 recruits TBK1-IKKε, and IRF3 is then activated to trigger type I IFN production." (PMID 36056146, 2022). "In this study, we demonstrated that viral infection induced the interaction of the transducer of ERBB2.1 (TOB1) with IRF3, which bound to the promoter region of Ifnb1 in macrophages." (PMID 36085336, 2022).
viral infection (continued). "Activation of these receptors enhances the release of anti-viral interferons to combat viral infection, activating NF-κB and interferon regulatory factor 3 (IRF3)." (PMID 36341332, 2022). "A recent report also showed YAP is activated upon activation of IRF3 antiviral signaling by viral infection." (PMID 35503798, 2022). "IRF3/5/7 constitutively reside in cytoplasm and following virus infection, they are translocated to nucleus for IFN transcription." (PMID 35464458, 2022). "Interferon regulatory factor 3 (IRF3) has been shown to be activated (through phosphorylation) by virus infection or by double-stranded RNA." (PMID 36298693, 2022). "In the present study, we determined that viral infection markedly induced the interaction of TOB1 with IRF3, which is bound to the promoter region of Ifnb1 in macrophages." (PMID 36085336, 2022). "In the case of the RLR–MAVS complex, the adaptor MAVS was reported to induce the formation of large, prion-like aggregates to activate IRF3 and propagate interferon-mediated response upon viral infection." (PMID 35979366, 2022). "Although MAVS is widely studied for mediating the activation of NF-κB and IRF3 in response to viral infection, MAVS also plays a critical role in central nervous system inflammation and metabolism." (PMID 35850307, 2022). "We next examined key molecules in the RIG‐I pathway and found that TBK1 and IRF3 phosphorylation was severely compromised in response to viral infection despite restoration of MAVS level following protease inhibitors treatment." (PMID 36216581, 2022). "We examined the nuclear localization of the transcription factors IRF3, NF-κB, and pSTAT1, which play key roles in the elaboration of the type I interferon response to viral infection and which are major targets for inhibition by other viruses." (PMID 35319251, 2022). "Several TRIMs were also recruited to negatively regulate the activation or stability of TBK1 and IRF3/7 during virus infection." (PMID 36498930, 2022). "IRF3 acts as a transcription factor that generates type I IFN production in the early phases of virus infection." (PMID 36498930, 2022). "In the current report, we found that IAV infection increases MAGI1 expression and enhances virus infection by inhibiting various anti-viral responses including STATs and IRF3 activation and induction of MX1 and OAS2." (PMID 36082118, 2022). "TBK1 undergoes autophosphorylation and ubiquitination to facilitate the activation of downstream adaptors (e.g., IRF3 or NF-κB) during viral infections." (PMID 35412346, 2022). "Among them, OTUD4 is induced in an IRF3/7-dependent manner, and OTUD1 increases the stability of MAVS during viral infection by directly removing the K48-linked ubiquitination of MAVS, thereby promoting RLR-mediated innate immune signals." (PMID 36505476, 2022). "In this case, ISGylation of IRF3 protects it from ubiquitination and proteosomal degradation, thereby critically sustaining IRF3 activity during viral infection." (PMID 35280283, 2022). "Upon virus infection, IRF3 is phosphorylated at its C-terminus by TBK1 and IκB kinase ε, and is translocated into the nucleus as a dimer." (PMID 33801464, 2021). "Interferon regulatory factor 3 (IRF3) is a key transcription factor activated in response to virus infection and is largely responsible for establishing an antiviral state in the infected host." (PMID 33805458, 2021). "Interferon regulatory factor 3 (IRF-3) is directly activated upon virus infection and functions as a key activator of interferon (IFN) genes." (PMID 34204411, 2021). "Viral infection triggers host innate immune responses by activating transcription factors, namely, IRF3 and NF-κB, which coordinately induce the production of type I IFNs." (PMID 33735323, 2021).
viral infection (continued). "A previous study demonstrates that mice deficient in IRF3 show impaired expression of IFN-γ by memory T cells during T cell responses to virus infection, suggesting that IRF3 is a positive regulator of oncogenic pathways involving IFN-γ15." (PMID 33479394, 2021). "While virus infection was required for FoxO1-mediated negative regulation of IRF3, the mRNA level of FoxO1 remained unchanged post-infection, suggesting posttranslational control of FoxO1 activity." (PMID 33805458, 2021). "Since IRF3 is a well known transcription factor governing expression of IFNs in innate immune response to viral infection, we next examined the influence of RDUR on the phosphorylation of IRF3 (p-IRF3) on Ser386." (PMID 34054851, 2021). "While the IRF3 functions are protective during virus infection, IRF3 activity can be detrimental to the host in other diseases." (PMID 34619149, 2021). "The acetylation of TBK1 at Lys241 during the early stage of viral infection enhanced the recruitment of IRF3 to TBK1." (PMID 32772249, 2021). "It has been reported that virus infection triggers the SUMOylation of mouse Irf3 on Lys152, resulting in the downregulation of type I IFN production." (PMID 33805458, 2021). "NSs expression alone was able to inhibit the nuclear translocation of IRF3 in response to a viral infection." (PMID 33397830, 2021). "This study suggests FoxO1 as a novel target for therapeutic intervention of viral diseases or IRF3-driven pathology." (PMID 33805458, 2021). "Similar to mammals, both irf3 and irf7 are responsive to viral infection in a fish monocyte/macrophage cell line (RTS11), as well as primary fish macrophages, suggesting that irf3 and irf7 have a role in the immune response of fish macrophages." (PMID 34484211, 2021). "Interferon regulatory factor 3 (IRF3) is the classic downstream molecule of RIG-I during viral infection." (PMID 34148549, 2021). "While the proapoptotic function of IRF3 protects against viral infections, it is also involved in harmful immune responses that trigger hepatocyte cell death and promote liver disease." (PMID 34619149, 2021). "Our study explores immune activation, using IRF3 and NF-κB as a read-out, in the context of full virus infection." (PMID 34166398, 2021). "The phosphorylated IRF3 dimerizes and translocates into the nucleus to stimulate the expression of type-I interferon, which is critical for controlling the spread of viral infection." (PMID 34016972, 2021). "Another ubiquitin ligase that negatively regulates type I IFN production during viral infections by modification of IRF3 is the RBCC protein interacting with PKC1 (RBCK1)." (PMID 33805458, 2021). "Meanwhile, the IRF3 polyubiquitination was examined using JMJD6-deficient cells and JMJD6-rescued cells upon virus infection with MG132 treatment." (PMID 33684176, 2021). "This process helps regulate the steady-state levels of IRF3 to finetune IRF3 activation during virus infection." (PMID 33805458, 2021). "Virus infection induces the nuclear localization of TRIM26, which promotes K48-linked polyubiquitination of activated IRF3 to degrade IRF3 and thereby attenuate IFNβ production." (PMID 34619149, 2021). "These dual functions of IRF3 work in concert to mediate protective immunity against virus infection." (PMID 33805458, 2021). "IKKε contributes to the type I interferon expression in response to viral infections, as it phosphorylates and, thus, activates IRF3/7 (interferon regulatory factor 3/7) transcription factors." (PMID 34298830, 2021). "Overall, these data indicated that TAP1 affected viral infections by regulating the TBK1/IRF3 signal pathway." (PMID 33925089, 2021). "Upon virus infection, K63-linked polyubiquitination of TRAF3 leads to the recruitment of TBK1 and the subsequent activation of IRF3 (54, –, 56)." (PMID 33975961, 2021).
viral infection (continued). "For example, upon viral infection, viral DNA or RNA is recognized by the cytosolic and endosomal sensing systems which require IRF3 and IRF7 for type I IFN induction." (PMID 34389779, 2021). "The complex then induces interferon (IFN) by phosphorylation of interferon regulatory factor 3 (IRF3) and informs the surrounding cells of a virus infection." (PMID 33342034, 2021). "In our earlier study we had seen that viral infection causes phosphorylation of TBK1, IRF3, and NF-κB (p65)." (PMID 34214498, 2021). "Phosphorylation of IRF3 and TBK1 is the hallmark of their activation, which is essential for type I IFN induction during viral infection." (PMID 34950606, 2021). "Phosphorylation of IRF3 induced by virus infection triggers a rearrangement of the helices responsible for autoinhibition, restructuring IRF3 to allow dimerization and expose the DNA-binding domain." (PMID 33805458, 2021). "As the central component of antiviral immunity, careful regulation of IRF3 activity is crucial to facilitate a robust immune response to viral infection." (PMID 34619149, 2021). "The transcription factor IRF3 plays a commander-like role in manipulating IFN-β transcription upon viral infection." (PMID 34966372, 2021). "This is reminiscent of the positive IRF7 feedback loop driven by IRF3-induced IFNβ that reinforces IRF3 transcriptional responses to virus infections." (PMID 33476326, 2021). "Below we will discuss the research advances of STING/TBK1/IRF3 isoforms in viral infections, systemic lupus erythematosus (SLE), and cancer." (PMID 34868032, 2021). "Given the established role of NF-κB and IRF3 signaling pathways in the cell’s innate response and clearance of viral infection, we used multiple approaches to examine the activation of these transcription factors following bRSV infection." (PMID 32878896, 2020). "During viral infection, K63-linked polyubiquitination of TRAF3 leads to the recruitment of TBK1-IKKε and subsequent activation of IRF3." (PMID 32562145, 2020). "It has been suggested that rSmp76 suppresses an established viral infection by upregulating interferon-β expression through the phosphorylation of the interferon regulatory factor 3, which enhances type-I IFN responses and thus inhibits viral infection." (PMID 32408604, 2020). "Further research needs to investigate the underlying mechanisms involved in promoting the activation of IRF3 by GTD after virus infection in macrophages." (PMID 33776755, 2020). "During viral infections, IRF3 is important in the early phase of inducing the transcription of IFN-α and IFN-β, which results in the IRF7 activation." (PMID 33664729, 2020). "IRF3 is a key molecule in viral infection-induced type I interferon signaling, while type I interferon signaling is a key signature in SLE pathogenesis." (PMID 32719713, 2020). "We found that the protein expression level of p-IRF3 was higher in ZC3HAV1-overexpressed cells after the viral infection by using ImageJ software." (PMID 32922375, 2020). "After viral infection, KPNA2 associates with IRF3 for nuclear import, and USP22 promotes this critical step by stabilizing KPNA2." (PMID 32645843, 2020). "IFIT5 is a member of the IFIT family, which can be triggered by viral infection and enhances the antiviral response by promoting IRF3- and NF-κB-mediated gene expression." (PMID 31865850, 2020). "IRF3 remains as an inactive monomer in the cytosol of the uninfected cells; upon virus infection, it gets phosphorylated, dimerized, and translocated to the nucleus." (PMID 32295140, 2020). "The A20/TNFAIP3 protein is a negative regulator of nuclear factor kappa B (NF-κB) and interferon regulatory factors 3/7 (IRF3/7), which are key transcription factors involved in the inflammatory/antiviral response of epithelial cells to virus infection." (PMID 32102364, 2020).